MX1 (MX dynamin like GTPase 1)
Diseases named in the same sentence as MX1 in open-access papers (continued):
Sharing a sentence is not in itself a finding about the gene and the disease.
viral infection (continued). "Strikingly, canonical ISGs such as MX1, IFITM1, and IFI6 were significantly upregulated (>100-fold) in STAG2−/− HT-29 cells compared to their WT counterparts, in the absence of any virus infection." (PMID 29662124, 2018). "Notably, we discovered upregulation of multiple ISGs, such as ZBTB16, MX1, OASL, RSAD2, CMPK2, and CXCL14 in the DiMNF treated primary cells, even in the absence of viral infection." (PMID 37672505, 2023). "Furthermore, expression of interferon-stimulated genes such as MX1 and OAS1 was blocked downstream of poly(I:C) transfection by JAK inhibition but not induced by viral infection or METTL3 knockdown." (PMID 33243990, 2020). "In particular, 8 genes (Mx1, EPSTI1, XAF1, IFI44L, GBP1, SAMD9, SAMD9L, and CMPK2) were expressed in the highly resistant cell lines HPAF-II and Hs766T but not the highly permissive cell lines MIA PaCa-2 and Capan-1 in the absence of virus infection." (PMID 27533247, 2016).
influenza (105 papers, 2008 to 2025). An acute viral infection of the respiratory tract, occurring in isolated cases, in epidemics, or in pandemics; it is caused by serologically different strains of viruses (influenzaviruses) designated A, B, and C, has a 3-day incubation period, and usually lasts for 3 to 10 days. "Activation of IFNAR/IFNLR leads to JAK–STAT-dependent induction of interferon-stimulated genes, among which MX1 is a prominent antiviral effector implicated in limiting influenza replication via interactions with viral nucleoprotein." (PMID 41012169, 2025). "This section discusses the diseases associated with MX1: influenza and subacute sclerosing panencephalitis (SSPE) and their possible connections to other genes." (PMID 38666857, 2024). "We therefore infected mice expressing functional Mx1 alleles (B6-Mx1) with the influenza virus strain hvPR8-ΔNS1 for a more–clinically relevant influenza model." (PMID 32527928, 2020). "Conventional C57BL/6 mice carry a defective Mx1 gene (Mx1-/-) are susceptible to influenza and other orthomyxoviruses, whereas congenic B6.A2G-Mx1 mice (Mx1+/+) that carry a functional murine Mx1 are resistant and served as positive controls." (PMID 33196685, 2020). "Mx was found to be protective in laboratory mice, as many lab strains were found to have isoforms of Mx1 with exon deletions that left these mice more susceptible to influenza infection than mice with intact Mx1." (PMID 32477965, 2020). "Mx1 inhibits viral replication by blocking the transcription of viral RNA, and a deficiency in this protein enhances susceptibility to influenza infection." (PMID 30696001, 2019). "Because Mx1 is an important intracellular regulator of viral replication, Mx1 deficiency increases susceptibility to influenza infection in mice." (PMID 30696001, 2019). "By conducting quantitative trait loci (QTL) mapping in combination with transciptomic-microarray profiling, the authors identified a novel allele within the anti-influenza Mx1 gene that was a major determinant of influenza pathogenicity." (PMID 28604586, 2017). "Many studies on influenza pathogenesis in mice were performed in classical laboratory strains which carry a mutation in the influenza resistance gene Mx1 first described in the A2G mouse strain." (PMID 26921172, 2016). "Due to these genes of large effect, many studies of these pathogens have been conducted within susceptible models (e.g. mouse models of influenza infection are almost universally Mx1-/- models)." (PMID 23468633, 2013). "The sequence variation at the Mx1 locus in mouse is poorly understood despite its well-known role in influenza susceptibility." (PMID 23468633, 2013). "It has long been known that susceptibility to influenza varies between inbred mouse strains because most laboratory strains carry a mutation in the Mx1 gene, which is a strong resistance locus for mouse-adapted influenza strains." (PMID 22438897, 2012). "Interestingly, neonatal mice with a functioning Mx1 gene remain just as susceptible to influenza challenge as their Mx1-negative counterparts." (PMID 37764023, 2023). "Diseases associated with MX1 include influenza and viral encephalitis." (PMID 37256135, 2023). "Similarly, MX1 upregulation is also important because it has been linked to the high resistance of the A2G mouse inbred strain to influenza infection." (PMID 34836388, 2021). "For example, functional Mx1 transfection diminished the polymerase activity of influenza virus, and functional Mx1-carrying mice are highly resistant against pathogenic influenza infection such as pandemic 1918 and lethal human H5N1, PR8, and avian H5N2 Ab/Korea/ma81/07 virus." (PMID 30696001, 2019). "In influenza, MX1 can generate a protective antiviral response by controlling the expression of key molecules associated with virus lethality." (PMID 37685953, 2023). "Cellular antiviral Mx1 in mice or MxA in humans can interact with NP and inhibit influenza replication." (PMID 37766365, 2023).
influenza (continued). "For example, MX1 can block influenza A by altering sorting of viral vesicles in the ER/Golgi intermediate compartment." (PMID 36757924, 2023). "IFN-stimulated genes (ISG) were also broadly upregulated in lethal disease, including canonical ISGs and genes that have been shown to be important in restricting influenza infection, such as MX1, ISG15 and IFITM1." (PMID 35271686, 2022). "MX1 (fold change = 8) is also a GTPase that blocks viral replication, and is widely studied in the Influenza infection." (PMID 33897690, 2021). "Recombinant Mx-1, modified to facilitate cell penetration, was capable of effectively suppressing influenza infection in vitro and in vivo." (PMID 34413772, 2021). "While MX1 from humans and mice as well as in other mammals such as rats, pigs and bats are potent anti-influenza A factors, in ducks and chickens, MX1 seems to be inactive against avian IAV." (PMID 33810083, 2021). "Both ISG15 and MX1 have been shown to protect against several viruses including influenza infection." (PMID 34836388, 2021). "The gene MX1 is an essential innate immune response gene to a wide variety of viral pathogens and key to host responses to influenza." (PMID 33187194, 2020). "Plasmacytoid dendritic cells are known to produce much of the initial IFN-α, and it is thought that the autocrine action of IFN-α on the pDCs upregulates antiviral factors such as Mx1 and thus protects against influenza infection." (PMID 32477965, 2020). "IFIT1, IFIT3, IFITM3, MX1, and ISG15 have all been shown to possess anti-influenza activities; however, a genetic variant of IFITM3 has been associated with severe influenza infection and higher hospitalization rate." (PMID 33347425, 2020). "Wild type mice treated with exogenous interferon had a higher survival rate and lower viral titers compared to MX1-/- mice after influenza A/H1N1 and A/H5N1 infections." (PMID 33347425, 2020). "Mx1-9R treatment inhibited viral replication and RNA expression in the infected cells, and treatment with Mx1-9R prior to influenza exposure increased murine resistance against influenza by restricting the viral propagation." (PMID 30696001, 2019). "Genes such as Irf7, Irf9, Mx1, Ifit3, Oas1a (L5) were induced most highly in lungs of virally infected mice (influenza and RSV)." (PMID 31253760, 2019). "The first anti-influenza restriction factor to be discovered, the murine protein Mx1, was initially described over 50 years ago." (PMID 28346537, 2017). "Mammalian MxA-like proteins, such as human MxA or mouse Mx1, are known to be potent inhibitors of influenza and a broad range of other viruses." (PMID 28197148, 2017). "In rodents, Mx1 and Mx2 localise to the nucleus and cytoplasm, respectively, and this correlates with their antiviral profile; Mx1 inhibits influenza and other viruses that replicate in the nucleus whereas Mx2 inhibits viruses that replicate in the cytoplasm." (PMID 29215570, 2017). "Others have identified genes that are protective during influenza infection, including MX1, NCR1, CCR5, IFITM3 and IL1014." (PMID 27156515, 2016). "Nevertheless, the use of Mx1 transgenic pigs offers a novel approach to explore avenues to prevent and control the evolution and the spread of pandemic influenza strains or CSFV." (PMID 25408889, 2014). "Another study suggested the possible regulation of influenza virus infection by miR-155 in chickens due to its targeting of the chicken anti-influenza gene MX1 and activation of the JUK pathway." (PMID 25266911, 2014). "Horisberger reviewed the data on the relationship between the Mx1 gene and influenza as it stood in 1995 (see section on Mx1)." (PMID 22438897, 2012). "Induction of the type I interferon response during influenza infection appears to be important in both human and mouse models, as evidenced by the increased expression of genes including Irf1, Ifi202, Oas1, and Mx1 in mouse microarray studies." (PMID 22110538, 2012).
influenza (continued). "Numerous studies have since confirmed the critical importance of Mx1 for influenza resistance in mice, independent from other IFN-induced genes." (PMID 20808435, 2010). "Therefore, D2-Mx1r/r mice carrying a functional Mx1 gene represent an improved in vivo model for investigating the host responses and possible intervention strategies for severe influenza infections and disease in humans." (PMID 38360537, 2024). "The crucial role of MX1 in influenza resistance has been well documented in mouse and human studies, where it was shown to prevent the transcription and replication of viruses that utilize nuclear replication by preventing the transcription of viral RNA polymerase." (PMID 38932231, 2024). "However, we found a decrease in the expression of Mx1 and Oasl2 in the empagliflozin treatment group when compared with vehicle controls during influenza infection." (PMID 38112660, 2023). "At most, we knew that the corresponding gene was located on chromosome 26, that two spots were detected using antisera raised against human MxA on an electrophoresis gel of total proteins extracted from equine cells exposed to IFN-α, and that equine Mx1 exerted anti-influenza activity." (PMID 37243140, 2023). "However, siMAGI1 leads to the inhibition of influenza infection, which was in part due to the induction of MX1." (PMID 36082118, 2022). "One group of ISGs, as represented by several well-known anti-influenza ISGs (Gbp3, Ifit3, Isg15, and Mx1/2), showed a kinetic pattern of mRNA expression largely resembling that of IFN-γ mRNA, suggesting that they were likely to be directly regulated by IFN-γ in an autocrine manner." (PMID 35296070, 2022). "The introduction of the Mx1 gene in mice lacking the Mx1 allele leads to influenza-resistant mice whereas transfer of the same gene in swine does not result in viral-resistant pigs." (PMID 36439341, 2022). "MX1, OASL and IFIT5 genes encode proteins with known functions in influenza defense." (PMID 32381003, 2020). "In this study, we examine whether relative humidity impacts host responses to influenza infection using Mx1 congenic mice." (PMID 31085641, 2019). "Most inbred mouse strains (e.g., C57BL/6 and BALB/c) have nonfunctional mutant Mx1, and mice from these strains are highly susceptible to influenza infection." (PMID 30696001, 2019). "Finally we wanted to study the inhibitory effects of the Mx1 transgene on a virus other than influenza." (PMID 25408889, 2014). "Besides influenza, Mx1 is also expected to lead to resistance for other severe swine infectious viruses such as CSFV." (PMID 25408889, 2014). "Despite the large effect of Mx1 on influenza response, there was large phenotypic variation within both the functional and non-functional Mx1 allele classes." (PMID 23468633, 2013). "One study demonstrated that miR-155 might target the chicken anti-influenza gene MX1 and activate the JUK pathway, therefore regulating influenza virus infection in chickens." (PMID 24066118, 2013). "A key host response QTL was located at the site of the known anti-influenza Mx1 gene." (PMID 23468633, 2013). "Based on target prediction, miR-155 could target the chicken anti-influenza gene MX1, therefore playing a role in host and AIV interactions in chickens." (PMID 22726614, 2012). "Especially because Mx1 is a known potent anti-influenza gene." (PMID 22384400, 2012). "Murine Mx1 and human MxA mediate their anti-influenza effects via distinct mechanisms: Mx1 is nuclear and inhibits primary transcription of the virus genome, while the cytoplasmic human MxA protein affects an ill-defined post-transcriptional step probably via an interaction with the nucleoprotein." (PMID 20808435, 2010). "Consequently, in Mx1+/+ mice, virus-induced IFN activates the Mx1 gene in addition to other antiviral genes, leading to a more complete innate immune response and more robust resistance to influenza and influenza-like viruses." (PMID 18787692, 2008).
influenza (continued). "As such, a lack of MX1 has been shown to increase susceptibility of mice to influenza." (PMID 40316897, 2025). "Humans carry a functional MX1 gene but may still experience severe influenza disease." (PMID 38360537, 2024). "While the antiviral protective mechanism of IRF7 in the immune response is well defined, there is evidence suggesting that MX1 may exert its anti-influenza protective effect by downregulating factors such as IL-6, IL-1β and TNFα, among others, involved in excessive cytokine response." (PMID 38932312, 2024). "The myxovirus resistance protein 1 (Mx1/MxA), an interferon-induced GTPase that belongs to the dynamin superfamily of large GTPases, is one of the host-cell innate immune response mediators that has antiviral activity against several RNA viruses, including influenza." (PMID 38249300, 2023). "In summary, these results strongly suggested that an ethanolic extract of Meliae Fructus inhibited influenza A virus infection by affecting viral entry, PA proteins of the RNA polymerase complex, and Mx1 induction and may be a potential and novel anti-influenza agent." (PMID 28400751, 2017). "We observed increased expression of Stat1, Stat2, Mx1, Oasl2, CCL2, CCL3, CXCL9, and CXCL10 in influenza-infected hearts and lungs when compared to PBS-treated controls." (PMID 38750107, 2024). "We next assessed expression levels of various cytokines and chemokines (i.e., IFNB1, IFNL1, IFNL2/3, IFIT1, IFIT3, OAS1, MX1, IL‐6, CXCL10, and IFITM1) which were triggered by influenza and OC43 virus infections alone or together by qPCR." (PMID 38556468, 2024). "We infected both C57BL/6 and STAT1−/− mice with influenza or PBS control and then measured the relative expression of Mx1 and the chemokine CXCL10." (PMID 38750107, 2024). "In conclusion, the antiviral state induced from prolonged primary HRV infection mediated by RIG-I and ISGs (including MX1 and IFITM1) can confer a protective innate immune defense mechanism against secondary influenza infection." (PMID 37190061, 2023). "The first investigation of two duck Mx1 alleles found that they did not confer resistance to influenza infection in stably-transfected mouse and chicken cell lines, but the intracellular distribution of the recombinant protein differed from the positive control mouse Mx1." (PMID 30634569, 2019). "Our study further indicated that rosiglitazone treatment decreased downstream signaling agents STAT1, STAT2, and the ISGs Mx1, CXCL9 and CXCL10 during influenza infection." (PMID 31159430, 2019). "Thus, Mx1 could be another efficient target of anti-influenza therapy." (PMID 30696001, 2019). "Pretreatment of mice with type I IFNs 8 h before H5N1 influenza infection did protect against high viral loads and host mortality; however, this was only in mice positive for the potent influenza restricting ISG, Mx1 (Tumpey and others 2007)." (PMID 25714109, 2015). "Subsequently, most studies of host genetic contributions have used naturally defective Mx1 mouse strains, such as C57BL/6J to study the effect of gene knock-outs on the host response to influenza." (PMID 23468633, 2013). "In such a situation, ISGs such as IRF7, MX1 and ISG15 are unable to elicit antiviral effects against some severe influenza strains resistant to these genes, while IFTIM can elicit antiviral effects and circumvent fatal events associated with severe influenza pandemic viruses." (PMID 38932312, 2024). "On the other hand, the same functional Mx1 gene in the DBA/2J mouse strain (D2-Mx1r/r) does not confer protection against severe disease after influenza infection." (PMID 38360537, 2024). "The differential temporal expression of MX1 and IFI27 in the SARS-CoV-2 challenge model was replicated in challenge experiments with multiple influenza strains, respiratory syncytial virus, or rhinovirus, and in data from household contacts with naturally acquired SARS-CoV-2 infection." (PMID 39616162, 2024).
influenza (continued). "In a recent study, the influenza A virus NP-positive cell fraction did not vary significantly in the presence of canine Mx1, suggesting, as in previous studies, that it is not endowed with anti-influenza activity." (PMID 37243140, 2023). "The antiviral role of MX1 is well studied in human negative-strand RNA virus infections such as influenza." (PMID 34578316, 2021). "The MDCK cells do not have a robust Mx1 and Mx2 response to influenza and this has been correlated with changes in the polymerase and NS segments." (PMID 32925936, 2020). "Further, Mx1-9R-treated mice demonstrated normal T-cell responses against influenza infection, and showed no significant changes in antigen-specific cytotoxic CD8 T cell populations in the lung compared to untreated mice." (PMID 30696001, 2019). "Reduction of STING gene expression or other anti-viral factors (e.g. IFNB1, MX1, ISG15) by apocynin, may in part, explain the slight increase in influenza gene transcription following apocynin treatment." (PMID 30341336, 2018). "The identification of a QTL of major effect sitting over the anti-influenza gene Mx1 was not surprising." (PMID 23468633, 2013). "Jointly considering our new results at DNA methylation levels and the earlier discovery of IFI27 in COVID-19 infections, it may be safe to infer that the CpG site cg16785077 (MX1) played a role in SARS-CoV-2 transmissions and led to influenza-like symptoms through IFI27 (NP/OP)." (PMID 38666857, 2024). "The expression of interferon response genes STAT1, STAT2, Mx1, OASL2, ISG15, chemokines CCL2, CCL3, CXCL9 and CXCL10, and the frequency of neutrophils (CD45+CD11b+Ly6G+) and CD4+ T cells (CD45+CD4+) were all significantly increased in influenza-infected mice when compared to vehicle controls." (PMID 38750107, 2024). "Notably, unlike WT Mx1 mice, caspase-1/11 KO Mx1 mice were spared from influenza disease exacerbation even when preconditioned in low ambient humidity of 10% RH." (PMID 31085641, 2019). "Finally, MDCK cells do not have a robust Mx1 and Mx2 response to influenza." (PMID 32925936, 2020). "While it has to be confirmed whether influenza‐infected ferrets or indeed humans show similar responses to IFN treatment, this is to our knowledge the first time that IFNαβ‐driven immunopathology has been demonstrated to outweigh the protective effect of the IFN‐induced potent anti‐IAV protein Mx1." (PMID 27520969, 2016).